PDK4 (pyruvate dehydrogenase kinase 4)
Diseases named in the same sentence as PDK4 in open-access papers (continued):
Sharing a sentence is not in itself a finding about the gene and the disease.
mitochondrial disease (1 paper, 2025). "Eye muscles show no ISRmt but activate PDK4—inhibitor of glucose oxidation—thereby upregulating beta‐oxidation, which is non‐optimal in mitochondrial disease and can explain eye muscle atrophy in mitochondrial disease." (PMID 40681476, 2025).
neurological disorders (1 paper, 2023). "Studies are needed to evaluate the detailed mechanism and function of PDK4 in ED and other vascular and/ or neurological disorders." (PMID 38104056, 2023).
peripheral neuropathy (1 paper, 2024). A disorder affecting the peripheral nervous system. "However, DCA has severe systemic side effects, including peripheral neuropathy, necessitating the development of alternative PDK inhibitors, especially those targeting PDK4." (PMID 39122684, 2024).
PDK4 also shares sentences with these, for which no sentence is quoted: colorectal (3 papers); ischemic heart disease (3); osteoarthritis (3); Atrophy (2); benign tumors (2); inflammatory bowel disease (2); ischemia (2); lymph node metastasis (2); myopathy (2); pulmonary hypertension (2); rhabdomyosarcoma (2); abdominal aortic aneurysm (1); acute lung injury (1); acute myeloid leukemia (1); adenocarcinoma (1); age (1); age-related macular degeneration (1); alcohol (1); Alexander disease (1); allergies (1); aortic valve calcification (1); autoimmune disorder (1); B-cell acute lymphoblastic leukemia (1); brain diseases (1); breast tumours (1); Cerebral ischemia (1); cervical tumor (1); clear cell renal cell carcinoma (1); cognitive deficits (1); COVID-19 (1).
A further 27 diseases each share a sentence with PDK4 in 1 paper.